ARRDC5 (arrestin domain containing 5)
Description:
Plays an essential role in spermatogenesis. May be involved in the anchoring of the sperm head to the tail during spermatogenesis by affecting SEC22A-mediated SUN5 and NDC1 transport and localization.
Gene: Protein-coding gene on chromosome 19 (4,890,437 to 4,902,948, reverse strand). Ensembl gene ENSG00000205784.
Subcellular location: Membrane
Genetic constraint (gnomAD): Loss-of-function variants: 12 observed, 14.48 expected, observed/expected ratio (o/e) 0.83, 90% interval 0.53 to 1.34. The upper end of that interval is the gene's LOEUF score, 1.34, which puts it in group 5 of 6, group 1 being the genes least tolerant of losing a copy. Missense variants: 406 observed, 438.99 expected, observed/expected ratio (o/e) 0.92, 90% interval 0.85 to 1. Synonymous variants: 181 observed, 182.23 expected, observed/expected ratio (o/e) 0.99, 90% interval 0.88 to 1.12.
Homologues: Orthologues: chimpanzee ARRDC5 (98% identical), macaque ARRDC5 (92% identical), dog ARRDC5 (83% identical), pig ARRDC5 (82% identical), rat Arrdc5 (71% identical), mouse Arrdc5 (69% identical), guinea pig ARRDC5 (65% identical), Drosophila melanogaster CG3014 (22% identical), Drosophila melanogaster CG2641 (21% identical), Caenorhabditis elegans arrd-16 (20% identical), zebrafish si:ch211-130m23.2 (20% identical), Drosophila melanogaster CG1105 (20% identical), and 26 more. Paralogues in human: ARRDC2 (23% identical), ARRDC3 (23% identical), ARRDC4 (23% identical), ARRDC1 (20% identical), TXNIP (20% identical).
Diseases named in the same sentence as ARRDC5 in open-access papers:
ARRDC5 is named in the same sentence as 8 diseases in open-access papers, as found by Europe PMC text mining. Sharing a sentence is not in itself a finding about the gene and the disease. The quoted sentences say what the papers report.
breast invasive carcinoma (1 paper, 2024). "Larger bubbles indicate a stronger correlation, with ARRDC5 demonstrating a positive correlation between CNV and expression in breast invasive carcinoma." (PMID 39697539, 2024).
colorectal cancer (1 paper, 2014). A primary or metastatic malignant neoplasm that affects the colon or rectum. "To do this, we selected a small sub-group of these genes that remained transcriptionally silenced in the colorectal cancer cell lines HCT116 and SW480 (ARRDC5, C4orf17, C20orf201, DDX4, NT5C1B, STRA8, TDRD12)." (PMID 25594001, 2014).
Infertility (1 paper, 2023). "Collectively, these results demonstrate that ARRDC5 is required for the generation of morphologically normal sperm and genetic deficiency leads to OAT and infertility." (PMID 37069147, 2023).
pancreatic cancer (1 paper, 2021). "Previous studies have confirmed that ARRDC5 gene polymorphism is associated with colorectal and pancreatic cancer susceptibility." (PMID 34844217, 2021).
sterility (1 paper, 2023). "Through phenotyping analysis, the impact of ARRDC5 deficiency was found to be male-specific sterility due to significant reductions in sperm numbers and motility and increased abnormal sperm morphology." (PMID 37069147, 2023). "Considering the array of abnormalities observed with sperm from ARRDC5-deficient mice, the cause of sterility could be multifaceted, including defective capacitation or inability to fuse with the oocyte plasma membrane at fertilization." (PMID 37069147, 2023).
viral infection (1 paper, 2024). "For instance, ARRDC5 is closely associated with diseases resulting from viral infection and cardiovascular conditions." (PMID 38270169, 2024).
cancer (2 papers, 2018 to 2024). A tumor composed of atypical neoplastic, often pleomorphic cells that invade other tissues. "Several genes, including ARRDC5, ELF5, FIBCD1, LINC00494, NLRP7, and L1CAM, have been implicated in various aspects of cancer progression and metastasis." (PMID 39697539, 2024). "Through comprehensive genomic, epigenomic, and transcriptomic dissections, we pinpointed ARRDC5, ELF5, FIBCD1, LINC00494, NLRP7, and L1CAM as possible prognostic indicators across multiple cancer types." (PMID 39697539, 2024). "This comprehensive analysis emphasized ARRDC5 and NLRP7 as the most consistently dysregulated genes across multiple cancer types, underscoring their critical role in cancer biology." (PMID 39697539, 2024). "In this study, we examined the expression patterns of seven core genes (ARRDC5, ELF5, FIBCD1, LINC00494, NLRP7, L1CAM) across multiple cancer types using a combination of unpaired and paired samples, along with data from the TCGA-GTEx datasets." (PMID 39697539, 2024). "Although the roles of genes like ARRDC5 and ELF5 in cancer progression have been studied, their pan-cancer significance across different cancer types has not been fully demonstrated." (PMID 39697539, 2024).
ARRDC5 also shares sentences with these, for which no sentence is quoted: osteoarthritis (1 paper).